ALB (albumin)
Diseases named in the same sentence as ALB in open-access papers (continued):
Sharing a sentence is not in itself a finding about the gene and the disease.
glomerular disease (continued). "Patients with MCD had the highest level of 24-hour urinary albumin excretion compared with the patients with other glomerulopathies." (PMID 24244321, 2013). "Renal disease, as evidenced by excretion of increased amounts of albumin in urine due to a glomerulopathy, is a common end-organ complication in SCD." (PMID 21533141, 2011). "The baseline TG levels were independently associated with male sex, eGFR, BMI-SDS, a diagnosis of glomerular disease, a shorter time of CKD, diastolic blood pressure, serum hsCRP and serum albumin levels, and, in contrast to all other measured lipids, the fasting status." (PMID 38720111, 2024). "Compared to dogs with Cushing's syndrome, dogs with glomerular disease had significantly greater % of tubular (P < 0.001) and % glomerular (P < 0.001) proteins, greater absolute concentrations (g/L) of albumin (P < 0.001), tubular (P < 0.001) and glomerular (P < 0.001) proteins in the urine." (PMID 38053473, 2023). "Moreover, patients with low albumin had lower rates of glomerular disease, lower residual renal function, and higher rates of ACEI use, cardiovascular disease, all-cause mortality, and cardiovascular mortality." (PMID 35983095, 2022). "Laboratorial tests showed BUN 99 mg/dL, creatinine 10.7 mg/dL, total cholesterol 155 mg/dL, LDL 79 mg/dL, triglycerides 277 mg/dL, albumin 3.1 g/dL, proteinuria 2.7 g/24 h, and negative screening for secondary causes of glomerulopathy." (PMID 34311745, 2021). "Albumin could also be lost via the kidneys in glomerular diseases or during burns as well as in high metabolic and catabolic states." (PMID 33299609, 2020). "Moreover, for microalbuminuria to occur, the tubular mechanisms for reabsorption of proteins must have been overwhelmed by large quantities of albumin presented to the proximal tubules as a result of glomerulopathy." (PMID 28250988, 2017). "Studies to examine whether podocytes isolated from healthy controls respond differently to albumin compared to those from patients with glomerular diseases are currently underway." (PMID 23382978, 2013). "We tested our hypothesis on a small number of pediatric patient kidney biopsies, future studies are needed to further investigate the overlapping cell signaling events between albumin endocytosis and proteinuria induced apoptosis in a wider range of glomerular diseases." (PMID 40313745, 2025). "Finally, the authors observed that pCS levels were positively associated with age, serum albumin, and non-Mediterranean residency and negatively associated with glomerular disease." (PMID 39195755, 2024). "Although current studies suggest that Cav-1 may regulate the progression of glomerular associated diseases by endocytosing of macromolecules (cholesterol or albumin), the mechanism by which Cav-1 modulates the development of glomerular diseases requires further study." (PMID 34955837, 2021). "Thus, an additional mechanism by which anti-proteinuric therapies are beneficial in the treatment of glomerular diseases may be a reduction in injury to the podocyte by albumin." (PMID 23382978, 2013). "After removing the cases with concomitant glomerular diseases or renal calcinosis, the correlation between urinary protein-creatinine ratio (UPCR) and eGFR or serum albumin levels were evaluated by Pearson’s correlation (r)." (PMID 40304822, 2025). "As IgG has twice the molecular weight of albumin (±150 kDa), the occurrence of TKI-related IgG-uria indicates the severe onset of potential glomerular disease." (PMID 38288036, 2024). "Correlation analysis showed absence of correlation between the SWV and dispersion slope of occult blood, serum creatinine, 24-h urine protein, blood albumin, BMI and ROI box depth of children with glomerular disease." (PMID 37858094, 2023). "Compared to dogs with glomerular disease, dogs with Cushing's syndrome had a significant lower number of LMW (P < 0.001) and HMW (P = 0.0017) bands and greater % of albumin (P < 0.001) in the urine electrophoresis." (PMID 38053473, 2023).
glomerular disease (continued). "Further, converse correlations between the relative TTP or HuR protein expression and urine albumin levels were observed, implicating TTP and HuR in glomerulopathy, podocyte injury, and inflammation in DKD patients." (PMID 32487989, 2020). "However, even early glomerular disease and loss of size and charge permselectivity in DM with increased albumin leakage may not cause microalbuminuria, if normal tubular function can reabsorb the excess albumin from the glomerular filtrate." (PMID 28840540, 2017). "Since albumin accounts for the majority of the urinary protein that passes across the defective glomerular filtration barrier, research efforts have been focused on deciphering the mechanism of albumin overload induced PTEC injury in glomerular diseases." (PMID 40313745, 2025). "The relationship between laboratory data, including UPCR, eGFR, and serum albumin level, was analyzed in 124 patients without any concomitant glomerular diseases." (PMID 40304822, 2025). "Compared with other glomerulopathy groups, the DN group had a higher prevalence of DR and SBP, while the IMN group had a higher UTP level and anti-PLA2R antibody positive rate, but lower ALB, BUN, Scr, and eGFR (P < 0.05)." (PMID 37789020, 2023). "His tests showed proteinuria of 12.5 g/24 h, hematuria, serum creatinine 0.94 mg/dL, albumin 2.3 g/dl, total cholesterol 284 mg/dL, LDL 200 mg/dL, triglycerides 175 mg/dL, and negative screening for secondary causes of glomerulopathy." (PMID 34311745, 2021). "It will also be interesting to define whether SHIP2 inhibition in glomerular diseases presenting with increased leakage of albumin, such as DKD, show increased tubular uptake of albumin achieved by SHIP2 inhibition." (PMID 31342643, 2020). "Patients were included if presenting with NS from September 2006 to January 2012, a P-albumin < 30 g/L, and renal biopsy confirming non-diabetic, glomerular disease." (PMID 31023275, 2019). "The co-occurrence of glomerular disease increases the variability of urine albumin excretion, which may explain why uACR/uPCR is not as reliable as uPCR-uACR in determining the severity of TI." (PMID 39963635, 2025). "Urinary CD80 adjusted for urinary creatinine correlated negatively with baseline serum albumin in all patients, regardless of glomerulopathy (r = −0.5, p < 0.0001), whereas it correlated positively, albeit weakly, with baseline proteinuria (r = 0.31, p = 0.006)." (PMID 36673014, 2023). "We next analyzed the correlation of urinary B7-1 with estimated glomerular filtration rate (eGFR), albumin/urine creatinine ratio (ACR), a marker of glomerular proteinuria, and β-2-microglobulin (β2-MG), a marker of tubular proteinuria, in clinical cohort of patients with glomerular diseases." (PMID 35710882, 2022). "Thus, we suggest that the lower level of proteinuria in the 5-LO–/– groups in this animal model is due to the increase in albumin endocytosis in PT cells rather than in albumin permeability as has been suggested for glomerulopathies." (PMID 25302946, 2014). "The discovery cohort consisted of patients diagnosed with nondiabetic glomerular diseases with an average age of 39 years, a 5-year follow-up period, an estimated glomerular filtration rate (eGFR) average of 74 mL/min/1.73 m2, and a urinary albumin to creatinine ratio (uACR) average of 1.89 mg/mg." (PMID 40059827, 2025). "In pediatric CKD, proteinuria may result from increased excretion of albumin (as is common in adult and pediatric patients with glomerular disease) or non-albumin proteins due to tubulointerstitial diseases (which are more common in pediatric CKD) or a combination of the two." (PMID 38509517, 2024). "However, we could not observe any signs of glomerular disease based on histological analyses as well as urinary albumin-to-creatinine ratios." (PMID 27759104, 2016).
glomerular disease (continued). "Among the patients without any concomitant glomerular disease or renal calcinosis, UPCR was negatively correlated with eGFR (r = − 0.531, p < 0.001) and serum albumin level (r = − 0.352, p < 0.001)." (PMID 40304822, 2025). "According to the latest KDIGO guidelines, the albumin excretion rate and the ACR are not commonly used in nondiabetic forms of glomerular disease." (PMID 35093023, 2022). "Spot urine protein and albumin excretion were greater in patients with previous diagnosis of AMR and recurrent glomerular disease than in patients with T-cell rejection or other non-rejection findings." (PMID 34022831, 2021).
leukocytosis (75 papers, 2009 to 2025). "Literature suggests old age, elevated creatinine, low albumin, and leukocytosis as risk factors for the development of various complications in scrub typhus." (PMID 41356643, 2025). "Established risk factors for adverse outcomes in CDI include leukocytosis, elevated creatinine, older age and low serum albumin." (PMID 35093158, 2022). "Data from a large sample of SS/PD patients referred to a tertiary care hospital showed that 45% of patients had at least one CSF abnormality (leukocytosis, elevated protein, elevated albumin quotient, or intrathecal antibody production) and/or an autoantibody." (PMID 40869088, 2025). "The observed changes in albumin/globulin ratio, leukocytosis, neutrophilia, monocytosis, and lymphoid hyperplasia are consistent with an immunostimulatory response, supporting the proposed mechanism of action for CPMV." (PMID 40276251, 2025). "On the other hand, leukocytosis, thrombocytosis, and slightly decreased serum albumin levels were also indicative of incomplete KD." (PMID 39600774, 2024). "Tenderness, peritonitis, loose motion, increasing age, increased creatinine, leukocytosis, low albumin levels, and a history of CLD were independent predictors of mortality." (PMID 39139323, 2024). "Our study found that increased age, elevated creatinine, low albumin, leukocytosis, low platelet count, and elevated total bilirubin were associated with increased risk of 30-day mortality in CDI patients." (PMID 35093158, 2022). "All of them had NLR ≥ 3.3, majority of them leukocytosis and lowered level of total protein and albumin, at the time of their presentation." (PMID 35795064, 2022). "Other studies found biological factors such as leukocytosis, lymphocytopenia, albumin levels, serum lactate dehydrogenase levels, and CRP levels to carry predictive value." (PMID 35501514, 2022). "Logistic regression performed for significant variables found in the univariate analysis showed leukocytosis, high neutrophil-lymphocyte ratio (NLR), low albumin, high ferritin and D-dimer associated higher odds of death." (PMID 34646702, 2021). "Biologically, IVIg unresponsiveness was associated with inflammation (high CRP and procalcitonin levels, leukocytosis, low albumin level and high lymphocyte count) and hepatic involvement (high AST, ALT and gamma-glutamyl transpeptidase [GGT] levels)." (PMID 32080307, 2020). "As a result, metabolic acidosis, hypernatremia, early hyperkalemia (up to 6.6 mmol/l in the first hours) or hypokalemia (3.3 mmol/l), leukocytosis, increased creatinine, bilirubin, albumin, AST and ALT are observed." (PMID 32363201, 2020). "Laboratory tests were significant for a leukocytosis of 95 200/μL with 84% lymphocytes, smudge cells on peripheral smear, hemoglobin 13.2 g/dL, platelet count 177 000/μL, creatinine 1.2 mg/dL, serum albumin 2.1 g/dL, and hemoglobin A1c of 5.7%." (PMID 29568782, 2018). "In particular, it presents the average leukocytosis and serum albumin of the sample at the moment of the first evaluation." (PMID 28904744, 2017). "Except for leukocytosis, albumin and age, there was much heterogeneity in the variables used, and most studies were limited by small sample sizes." (PMID 22291926, 2012). "Odds ratios* for five laboratory values calculated per standard deviation for sodium, blood urea, albumin and uric acid and for leucopenia and leukocytosis for WBC." (PMID 20808904, 2010). "For advanced-stage HL, the International Prognostic Score (IPS) is widely used and incorporates seven variables: age ≥ 45 years, male gender, stage IV disease, hemoglobin < 10.5 g/dL, albumin < 4 g/dL, leukocytosis (≥15,000/mm3), and lymphocytopenia (<600/mm3 or <8% of the white blood cell count)." (PMID 40565831, 2025). "However, fever, leukocytosis, elevated CRP, ESR, procalcitonin, and ALP, along with decreased albumin, were significantly associated with pathogen isolation." (PMID 41010981, 2025).
leukocytosis (continued). "Similarly, no statistical associations were found between the CMV tissue density and levels of CRP, leukocytosis, albumin levels, or platelet count." (PMID 40725516, 2025). "Important clinical chemistry, hematology and histopathology findings included decreased albumin/globulin ratio, leukocytosis, neutrophilia, monocytosis, and lymphoid hyperplasia (Dunnett’s test, p<0.05) – these changes support the immunostimulatory mode of action for CPMV." (PMID 40276251, 2025). "In addition to albumin, this study found that leukocytosis at 4 weeks post-treatment affected the survival outcomes in dogs treated with the L-COP protocol." (PMID 38595652, 2024). "Normal laboratory test values: hemoglobin: females (12–16 g/dL), males (14–18 g/dL); leukocytes: leukocytosis (>11,000 white blood cells per microliter); albumin (3.5 to 5.5 g/dL); glucose (70 to 100 mg/dL); creatinine: males (0.7 to 1.3 mg/dL), females (0.6 to 1.1 mg/dL)." (PMID 38846234, 2024). "Leishmania seropositivity was significantly associated with weight loss, lymphadenomegaly, gingivostomatitis, and oral ulcers, as well as with reduced albumin and albumin/globulin ratio, increased total globulins and total proteins, leukocytosis, and thrombocytosis." (PMID 39160611, 2024). "Several poor prognostic factors, such as poor performance status, older age, number of metastatic organs, high serum lactate dehydrogenase (LDH) level, high serum CRP level, low serum albumin level, leukocytosis, high NLR, and visceral metastasis, were commonly mentioned in previous studies." (PMID 35781808, 2023). "Laboratory tests were notable for a leukocytosis 77 000/μL with 93% lymphocytes, hemoglobin 11.5 g/dL, platelet count 174 000/μL, creatinine 1.3 mg/dL, estimated creatinine clearance (CrCl) of 95 mL/min, and serum albumin 1.4 g/dL." (PMID 29568782, 2018). "Notice that the average leukocytosis was high (>9) and that the average serum albumin was low (<2)." (PMID 28904744, 2017). "Laboratory markers such as leukocytosis, increased creatinine levels, and decreased albumin or globulin levels may correlate with poor outcome for patients with CDAD." (PMID 19239754, 2009). "Many markers have been proposed, such as leukocytosis (in particular, neutrophils and eosinophils), increased inflammatory indices and a low serum albumin level, but they are common in other irAEs and, in general, may depend on the underlying neoplastic pathology." (PMID 37511260, 2023). "Laboratory investigations showed leukocytosis in 121 (80.7%), elevated liver enzymes (95 (63.3%) AST and 80 (53.3%) ALT), elevated ALP in 133 (88.7%), and low albumin levels (138 (92%)) in a significant proportion of patients." (PMID 38505450, 2024). "Clinical (fever, leukocytosis, elevated basal energy expenditure) or biochemical (CRP, albumin and prealbumin) indicators can be used, which can help to assess the presence of inflammation." (PMID 38337661, 2024). "Severe leukocytosis and higher CRP, as well as lower albumin levels, were common in AKI patients compared with non-AKI patients." (PMID 30942133, 2019).
vitamin D deficiency (75 papers, 2013 to 2026). A nutritional condition produced by a deficiency of VITAMIN D in the diet, insufficient production of vitamin D in the skin, inadequate absorption of vitamin D from the diet, or abnormal conversion of vitamin D to its bioactive metabolites. "The cross-sectional study performed on older adults with hip fracture identified low albumin levels as the only significant risk factor of vitamin D deficiency among the other potential risk factors examined." (PMID 40051558, 2025). "On the other hand, nutritional status like low albumin and vitamin D deficiency can trigger exaggerated immune responses, prolonging inflammation." (PMID 41036136, 2025). "In our previous study of 619 patients with chronic hepatitis C, low serum albumin levels were found to be associated with vitamin D deficiency [serum 25(OH)D3 level < 20 ng/mL]." (PMID 40142666, 2025). "Patients without vitamin D deficiency had a higher HDL level, while LDL-C, ALT, AST, and ALB were similar to those in the vitamin D deficiency group." (PMID 40751154, 2025). "A cohort of 509 patients revealed that 81% had biochemical evidence of protein malnutrition (albumin < 3.5 g/dL or total protein < 6.5 g/dL), and over 90% exhibited vitamin D deficiency, factors that compromise muscle and bone integrity." (PMID 40869488, 2025). "We screened a certain number of SNPs from each of 10 nutritional assessment phenotypes (BMI, WBFM, WC, hemoglobin, albumin, TC, vitamin D deficiency, UWP, right hand grip strength, and EA) for the genetic prediction of HF development." (PMID 38590862, 2024). "It was observed that older people with relevant vitamin D deficiency (<15 mg/dL) showed significantly lower albumin and ghrelin levels (p = 0.0015, p = 0.0397, respectively)." (PMID 36983369, 2023). "We addressed total 25-hydroxyvitamin D (25(OH)D), serum albumin, and uric acid (UA) levels, focusing mainly on vitamin D deficiency, as potential markers of LV systolic dysfunction in HF with reduced and mildly reduced ejection fraction (HFrEF, HFmrEF)." (PMID 38002259, 2023). "Compared with the vitamin D deficiency and D-insufficiency groups, the D-sufficiency group tended to have a higher level of serum albumin (P < 0.001) and estimated GFR (P < 0.001)." (PMID 38111622, 2023). "The risk of PMI in patients with IHD was 2.3 times higher than in non- IHD and increased to 3.1 in IHD patients with elevated PTH, to 3.9 in cases with vitamin D deficiency, to 4.4 if urea > 7.5 mmol/L, and to 4.5 if Urea/Albumin ratio ≥ 2.0." (PMID 36431261, 2022). "Vitamin D deficiency was the most prevalent (74.5%), followed by folate (33.5%), iron (32%), calcium (13%), vitamin B12 (10%), and albumin (5.5%) deficiency." (PMID 33026590, 2021). "We suggest that albumin and vitamin D deficiency are associated with several clinical conditions, including chronic intake insufficiency and acute consumption." (PMID 34966771, 2021). "Oral calcitriol supplementation; corrects vitamin D deficiency, retarding the albumin oxidation, decreases inflammation and suppresses iPTH secretion in a short follow up period." (PMID 30450134, 2018). "Postoperatively, vitamin D deficiency was still observed in 89.3% of adolescents, followed by albumin, ferritin, hemoglobin, iron, and other deficiencies (range, 4.6–38%)." (PMID 28822064, 2018). "Preoperatively, vitamin D deficiency was observed across most (96.4%) adolescents, followed by ferritin, albumin, iron, and other deficiencies (range, 4.7–39.4%)." (PMID 28822064, 2018). "Subjects with IBS were older (p = 0.004), had lower serum concentration of albumin (p = 0.01), and a significantly higher prevalence of vitamin D deficiency at a cutoff point of ≤50 nmol/L (53% vs. 27%, p = 0.001)." (PMID 28192499, 2017). "Vitamin D deficiencies and increases in urinary albumin excretion (UAE) are both important and potentially related health problems; however, the nature of their relationship has not been established in normoalbuminuric subjects." (PMID 24957097, 2014).